LCE1F (late cornified envelope 1F)
Description:
Precursors of the cornified envelope of the stratum corneum.
Synonyms: LEP6
Tractability: No criterion of Open Targets' tractability assessment is met for any kind of drug.
Gene: Protein-coding gene on chromosome 1 (152,775,140 to 152,777,024, forward strand). Ensembl gene ENSG00000240386.
Pathways (Reactome):
Developmental Biology: Formation of the cornified envelope
Gene Ontology:
Molecular function: identical protein binding; protein binding
Biological process: epidermis development
Genetic constraint (gnomAD): Loss-of-function variants: 8 observed, 8.4 expected, observed/expected ratio (o/e) 0.95, 90% interval 0.56 to 1.66. That is too few expected variants to judge how well the gene tolerates losing a copy. Missense variants: 154 observed, 151.1 expected, observed/expected ratio (o/e) 1.02, 90% interval 0.89 to 1.16. Synonymous variants: 67 observed, 59.04 expected, observed/expected ratio (o/e) 1.13, 90% interval 0.93 to 1.39.
Homologues: Orthologues: chimpanzee LCE1F (100% identical). Paralogues in human: LCE1E (94% identical), LCE1D (88% identical), LCE2D (70% identical), LCE2A (69% identical), LCE2C (69% identical), LCE2B (69% identical), LCE5A (68% identical), LCE3B (47% identical), LCE3C (47% identical), LCE3D (47% identical), LCE3A (46% identical), LCE3E (46% identical), and 8 more.
Diseases named in the same sentence as LCE1F in open-access papers:
LCE1F is named in the same sentence as 1 disease in open-access papers, as found by Europe PMC text mining. Sharing a sentence is not in itself a finding about the gene and the disease.
LCE1F shares sentences with these, for which no sentence is quoted: gastric cancer (1 paper).